AKT1 (AKT serine/threonine kinase 1)
Diseases named in the same sentence as AKT1 in open-access papers (continued):
Sharing a sentence is not in itself a finding about the gene and the disease.
meningioma (continued). "From the NGS study, recurrent mutations in TRAF and AKT1 were identified with a higher prevalence (17.5% and 12.5%, respectively) compared with grade 2/3 meningiomas reported in previous literature." (PMID 35774130, 2022). "We; thus, performed amplicon-based single-cell DNA sequencing on 7 samples of TRAF7 with KLF4 or AKT1, respectively, co-mutated meningiomas." (PMID 35984495, 2022). "Two NF2 unaltered meningiomas, localized at the olfactory groove and brain-invasive, had AKT1 E17K mutation." (PMID 33670055, 2021). "Although initially believed to be exclusive to grade I meningiomas, AKT1 mutation was found in 2% of grade II meningiomas in another recent study." (PMID 33670055, 2021). "From the embryological viewpoint, we found that the meningiomas harboring AKT1, SMO, KLF4, or POLR2A mutations were significantly associated with paraxial mesodermal origin." (PMID 33772057, 2021). "KLF4K409Q is the only mutation identified in the KLF4 gene associated with meningiomas, and like AKT1, it is commonly associated with TRAF7 co-mutation in meningiomas of the central skull base and sphenoid wings." (PMID 34638590, 2021). "These latter tumors mainly have meningothelial histotype and a low mitotic index, but a significantly higher recurrence rate than AKT1-mutated meningiomas at the same site." (PMID 34071391, 2021). "Mutations in TRAF7 have been identified in nearly one-fourth of meningiomas, while mutations in AKT1 and SMO have lower prevalence and are associated with higher grade NF2 wild-type tumors." (PMID 34300316, 2021). "In one case report, the AKT1 inhibitor AZD5363 was associated with modest tumor regression and prolonged local control when used as monotherapy in a case of recurrent meningioma with documented AKT1 mutation." (PMID 34638590, 2021). "AKT1 mutations predominately display meningothelial histology and are mostly seen in grade I meningiomas, occurring in 7–12% of grade I tumors." (PMID 33801089, 2021). "Our results were consistent with earlier studies that reported mutations in NF2, SMO, and AKT1 genes in atypical meningiomas, and we also observed mutations in MYBL2, a gene that was recently discovered." (PMID 32742192, 2020). "Future work is required to elucidate the role of M2 macrophages in meningiomas, and to uncover the mechanisms in which tumour cells harbouring a mutation such as AKT1 E17K can directly affect the tumour microenvironment." (PMID 32070062, 2020). "Focussing on WHO grade I meningiomas with different defined genotypes, NF2 meningiomas displayed a tendency towards higher M2 macrophage infiltrates when compared to AKT1 E17K-mutated tumours." (PMID 32070062, 2020). "Mutations in other known genes involved in meningioma pathogenesis such as AKT1 (E17K) and KLF4 (P238S) were marginally involved in one midline SB tumor, each from ED group #3." (PMID 31963394, 2020). "Meningioma with TRAF7 mutations can harbor mutations in KLF4 or AKT1 in 40% and 33% of cases, respectively." (PMID 30082628, 2018). "Oncogenic mutations in PIK3CA are observed in ~7% of non-NF2-mutant meningiomas, and occur mutually exclusive of AKT1 and SMO mutations, although they frequently co-occur with TRAF7 mutations." (PMID 27458586, 2016). "Another recurrent mutation in AKT1, located on chromosome 14q32, is observed in 6.8% of meningiomas and produces a glutamic acid to lysine substitution at codon 17 (E17K)." (PMID 27458586, 2016). "Mutations in SMO or AKT1/TRAF7 are most frequently observed in meningiomas of the anterior cranial base." (PMID 27458586, 2016). "Meningiomas with AKT1 mutations typically show chromosomal stability and are biologically benign." (PMID 40149634, 2025). "According to the 2021 WHO brain tumor classification scheme, convexity and the majority of spinal meningiomas have similar molecular findings (loss of chromosome 22q and/or NF2 mutations), while skull base meningiomas demonstrate different mutations (AKT1, TRAF7, SMO, and PIK3CA)." (PMID 36179256, 2022).
meningioma (continued). "NF2-mutated grade I tumors have a higher density of M2 macrophage infiltration than that of tumors with AKT1 activating mutations, suggesting that this genetic subset of grade I meningiomas may drive immunosuppression." (PMID 35712492, 2022). "In line with previous publications, we could validate the overlap of certain meningioma relevant mutations such as AKT1 and KLF4 with TRAF7 mutations." (PMID 35213082, 2022). "This confirms the association between AKT1 mutation and meningioma localization at the anterior or middle skull base and suggests that this genetic alteration might be correlated with brain invasion in the atypical histotype." (PMID 33670055, 2021). "Sequencing of skull-base meningiomas showed AKT1 mutations in ~30% of patients." (PMID 33801089, 2021). "Indeed, AKT1 mutation was previously found in two out of nine brain-invasive meningiomas and in only 1/81 atypical meningiomas classified according to WHO 2007, which do not include brain invasion among the diagnostic criteria." (PMID 33670055, 2021). "Similarly, in a series of 150 primarily grade 1 meningiomas, mutations in AKT1 occurred in 9% of tumors." (PMID 33346248, 2020). "We showed that AKT1 E17K-mutated meningiomas have a less immunosuppressive tumour microenvironment when compared to grade I NF2 meningiomas; this may explain why some NF2 tumours have high progression/recurrence rates." (PMID 32070062, 2020). "We did observe meningioma-related mutations in oncogenic AKT1, SMO, TRAF7, and NF2 gene." (PMID 32742192, 2020). "AKT1 mutations were found in more WHO grade I tumors than higher grade meningiomas (p = 0.020)." (PMID 31191822, 2019). "Interestingly, about 50% of all AKT1-mutated meningiomas also show alterations in TRAF7." (PMID 38137885, 2023). "In addition, NF2 alterations combined with abnormalities in AKT1 and mTOR are associated with the overgrowth of various tissues, which could be responsible for the recurrence of meningiomas." (PMID 35712491, 2022). "TRAF7, SMO, AKT1, and KLF4 mutations, referred to as “non-NF2,” are typically found in lower-grade meningiomas, characterized by fewer chromosomal abnormalities, and generally result in better clinical outcomes." (PMID 40725113, 2025). "In our study, we analysed the most common driver mutations (NF2, AKT1, KLF4, and TRAF7) in meningioma by genomics describing co-occurrences and new mutations." (PMID 40562609, 2025). "Most non-NF2 gene meningiomas are usually caused by mutations in SMO (9%) and AKT1 (30%), especially in the cases where the meningioma is at the convexity at the skull-based, respectively." (PMID 39329938, 2024). "NF2 wild-type meningiomas frequently harbor mutations in TRAF7, KLF4, AKT1, PIK3CA, and SMO and are enriched in skull-base meningiomas." (PMID 38571886, 2024). "Further frequent non-NF2 driver mutations in meningiomas include oncogenic mutations in TRAF7, KLF4, AKT1 and SMO, which are all mutually exclusive to NF2 mutations." (PMID 39273576, 2024). "FD is caused by a mosaic activating pathogenic variant in GNAS gene, and the development of sporadic meningiomas also has genetic predisposition including NF2, TRAF7, KLF4, AKT1 and TERT." (PMID 38287340, 2024). "In 2013, Clark and colleagues first described an association between WHO grade, histological subtype and the anatomical location of meningiomas with distinct molecular features, including mutations in TRAF7, KLF4, AKT1, SMO and NF2." (PMID 39273576, 2024). "TRAF7 mutations have been described in approximately 20–25% of all meningiomas and often co-occur with mutations in KLF4 or AKT1, which are in turn both mutually exclusive to each other." (PMID 39273576, 2024). "Mutations in the genes AKT1, SMARCB1, and SMO are rare in cases of atypical meningiomas, and mutations in the genes KLF4 and TRAF7 are associated with an indolent clinical behavior, thus making these meningiomas have a low risk of progression." (PMID 39202270, 2024).
meningioma (continued). "We found that VEGFA mRNA expression was almost 3-fold higher in KLF4 meningiomas compared to AKT1 tumors, in agreement with previous studies." (PMID 36937440, 2023). "We used RNA sequencing (RNA-seq) to determine whole transcriptome profiles of twenty meningiomas with genomic alterations including NF2 inactivation, loss of chr1p, and missense mutations in TRAF7, AKT1 and KLF4." (PMID 36937440, 2023). "NGS has led to the identification of novel driver gene mutations in meningioma in addition to NF2, including SMO, PI3KCA, TRAF7, KLF4, AKT1, POLR2A, and SMARCE1." (PMID 38066633, 2023). "Important driver mutations specifically associated with meningioma pathology (including NF2, TRAF7, SMO, PIK3C2B and AKT1) that were identified in the tissues were consistently found in spheroids." (PMID 38102708, 2023). "Since the majority of TRAF7 tumors harbor a gain-of-function mutation in a single amino acid position in either AKT1 or KLF4, AKT1E17K and KLF4K409Q appear to be the driving force behind TRAF7 meningioma growth." (PMID 36937440, 2023). "Stathmin-1 expression on the other hand is a known marker of PI3K-AKT pathway activation and is increased in AKT1 mutated meningiomas also showing tendency towards beneficial prognosis." (PMID 38023177, 2023). "On the other hand, some mutations such as TRAF7, PI3KCA, AKT1, and SMOs are frequently observed in WHO grade 1 meningiomas and, consequently, their therapeutic potential appears somewhat limited." (PMID 37760490, 2023). "AKT1 meningiomas displayed high relative levels of HTRA1 and transferrin genes relative to KLF4 tumors, while KLF4 tumors overexpressed CEACAM6, DEGS2, and TSPAN12 relative to AKT1 tumors." (PMID 36937440, 2023). "MC ben-1 meningiomas were enriched in NF2 mutations while the MC ben-2 subgroup was enriched in non-NF2 mutations including TRAF7, AKT1, KLF4, and SMO." (PMID 36840836, 2023). "Other non-NF2 mutational signatures that are prevalent in meningioma include TRAF7, AKT1, POLR2A, PIK3CA, KLF4, SMARCE1, and BAP1." (PMID 37887327, 2023). "In agreement with observed mutations in AKT1 and KLF4, TRAF7 meningiomas segregated into two distinct clusters." (PMID 36937440, 2023). "Mutations in Nf2, TRAF7, KLF4, AKT1, and SMO are present in approximately 80% of sporadic meningiomas." (PMID 37898750, 2023). "The mutation of TRAF 7 is frequently associated with mutations of AKT1 (which encodes for a kinase that regulates cell proliferation) or KLF4, and this combination is often linked to grade 1 meningiomas." (PMID 37760490, 2023). "PIK3CA mutations occur in about 7% of all meningiomas; they are mutually exclusive with NF2 and AKT1 and often associated with TRAF7 mutations." (PMID 38137885, 2023). "TRAF7 is mutated in about 20% of all meningiomas and is frequently associated with KLF4, AKT1, and PIK3CA mutations." (PMID 38137885, 2023). "GO analysis uncovered that the “extracellular matrix” gene set was the most representing in upregulated DEGs in AKT1 meningiomas, while KLF4 tumors upregulated DEGs important for “epidermis development” and “cell motility”." (PMID 36937440, 2023). "The AKT1 p.Glu 17 Lys mutation triggers the abnormal activation of the PI3K pathway, indicating a key role in meningiomas proliferation." (PMID 37760490, 2023). "The most frequent coding changes identified in non-NF2 meningiomas were missense mutations in TNF Receptor Associated Factor 7 (TRAF7), Kruppel-like factor 4 (KLF4), and RAC(Rho family)-alpha serine/threonine-protein kinase 1 (AKT1)." (PMID 36937440, 2023). "In 2013, two separate landmark studies utilized whole genome and whole exome sequencing to uncover novel mutations in non-NF2 meningiomas including TRAF7 (TNF receptor associated factor 7), KLF4 (Krüppel-like factor 4), AKT1, and SMO (Smoothened)." (PMID 36840836, 2023). "AKT1 mutations are demonstrable in anterior skull-base and convexity meningiomas, while SMO mutations are found in anterior skull-base meningiomas." (PMID 37760490, 2023).
meningioma (continued). "AKT1 meningiomas displayed increased expression of 1188 genes and decreased expression of 673 genes relative to KLF4 tumors." (PMID 36937440, 2023). "Conversely, a larger study on 3031 meningioma samples from 514 individual cases has shown that TRAF7, AKT1, and/or KLF4 mutations were significantly associated with a lower risk of progression." (PMID 35565385, 2022). "In validation cohorts, the AKT1 and SMO mutations were observed in skull base and higher grade meningiomas." (PMID 35402234, 2022). "TRAF7 is also one of four genes including KLF4, AKT1, and SMO, likely to be mutated in non-NF2 mutated meningiomas found at the skull base." (PMID 36686824, 2022). "Otherwise, 70% of TRAF7/AKT1-type meningiomas tend to localize in the anterior cranial fossa, at the medial portion of the middle cranial fossa, and at the level of the anterior convexity." (PMID 35892898, 2022). "AKT1-mutant meningiomas originate in the cervical spine ventrally to the spinal cord, are almost exclusively associated with meningothelial histology and exhibit no calcifications on imaging." (PMID 35943573, 2022). "In contrast to AKT1-mutant meningiomas, a substantial proportion of NF2-mutant meningiomas developed in the dorsal or dorso-lateral location to the spinal cord (59.3%, p = 0.0043, online resource)." (PMID 35943573, 2022). "Molecular analysis revealed that there were 152 NF2 meningiomas (54.1%) and non-NF2 meningiomas: 45.9% (129 cases) including “AKT1”: 11.4% (32 cases), “KLF4”:5.7% (16 cases), “POLR2A”:16 cases (5.7%), “SMO”: 0.7% (2 cases), and others:22.1% (62 cases)." (PMID 35570314, 2022). "Noteworthy, none of the cases had gene mutations typically observed in skull base meningiomas and involving AKT1, PIK3CA and SMO, while one case had co-occurring NF2 and SMARCB1 mutations previously found in sagittal meningiomas." (PMID 35049691, 2022). "A genomic study of 300 meningiomas showed mutations in TRAF7 in approximately 25% of all meningiomas, AKT1 mutations in 10-15% (affecting the PI3K signaling pathway) and KLF4 mutations in 10%." (PMID 36033542, 2022). "Since 40-60% of sporadic meningiomas have a loss of NF2 expression, meningiomas can be molecularly categorized into NF2 mutants and non-NF2 mutants, with the latter predominantly comprised of TRAF7, KLF4, AKT1, SMO, and P13K mutations." (PMID 35712492, 2022). "In their cohort of high grade meningiomas, most tumors were characterized by NF2 mutations, with very few tumors having mutations in TRAF7, KLF4, AKT1 and SMO, suggesting that high grade meningiomas have few targetable genetic mutations." (PMID 35402234, 2022). "A tumor location in the thoracic spine was significantly more common in NF2-mutant meningiomas (75%) than in their AKT1-mutant counterparts (26.6%) (p = 0.0034)." (PMID 35943573, 2022). "One exception to this was a recurring co-mutation AKT1 and TRAF7 that occurred in higher grade meningiomas with a low-grade cytogenetic background." (PMID 35299730, 2022). "Meningioma‐relevant mutations were present in 90/126 (71.4%) specimens including NF2, TRAF7, KLF4, SMO, AKT1,TERT promotor, ARID,SUFU, and PIK3CA mutations in similar frequencies compared to previous studies." (PMID 35213082, 2022). "Apart from NF2 alterations in sporadic meningiomas, various oncogenic mutations in KLF4, SMO, TRAF7, PIK3CA, AKT1 and POLR2A are also found to be clinically actionable genetic events in meningiomas." (PMID 34722286, 2021). "PIK3CA mutations are found in 4–7% of meningiomas and often cooccur with TRAF7 mutations but are exclusive of NF2, AKT1, and SMO mutations." (PMID 33801089, 2021). "Additional common pathological relevant genes of meningiomas, including AKT1 (n = 3; 8%), CDKN2A (n = 2; 5%), SMO (n = 0; 0%), SUFU (n = 0; 0%), POLR2A (n = 6; 16%), TRAF7 (n = 1; 3%), and SMARCB1 (n = 2; 5%), were observed as well." (PMID 34778063, 2021).
meningioma (continued). "The same case was also noted to have metastatic meningioma nodules in bilateral lungs and these lesions were also found to be stable after AKT1 inhibitor use." (PMID 34638590, 2021). "Neither tumor contained mutations in additional genes associated with meningioma (such as NF2 and AKT1) or malignancy, strongly implicating BAP1 inactivation in disease pathogenesis." (PMID 34504799, 2021). "Two independent studies have identified TRAF7 (TNF receptor-associated factor 7), AKT1 (v-akt murine thymoma viral oncogene homolog 1), and SMO (Smoothened, frizzled family receptor) mutations as drivers of meningioma oncogenesis." (PMID 34300316, 2021). "AKT1, KLF4, SMO, or POLR2A mutations were significantly more frequent in meningiomas of skull-base lesions than in those of supra-tentorial lesions (p = 8.3 × 10–11)." (PMID 33772057, 2021). "Based on these molecular features, several clinical trials in NF-2 wild type meningiomas, including targeted therapy for actionable mutations in PIK3CA, SMO, and AKT1 are ongoing (NCT02523014)." (PMID 33611710, 2021). "SMO and v-akt murine thymoma viral oncogene homolog 1 (AKT1) can lead to the activation of PI3K–AKT–mTOR pathway; it is relatively common and is associated with meningiomas localized in the skull base and with genomic stability." (PMID 34679551, 2021). "In particular, AKT1, KLF4, SMO, or POLR2A mutations were significantly more frequent in meningiomas of paraxial mesodermal origin than in those of neural crest (p = 1.7 × 10–10) and dorsal mesodermal origin (p = 3.0 × 10–4)." (PMID 33772057, 2021). "Pathogenic variants in AKT serine/threonine kinase 1 (AKT1), an oncogenic component of the (PI3K)-AKT-mTOR pathway, have been identified in non-NF2 meningiomas of the medial skull base." (PMID 33262459, 2021). "We comprehensively evaluated associations among tumor location, pathological diagnosis (histological type), and genetic alterations including AKT1, KLF4, SMO, POLR2A, and NF2 mutations and 22q deletion in 269 meningioma cases." (PMID 33772057, 2021). "The development of a molecularly driven trial of patients given targeted therapy based on their AKT1, SMO, and NF2 pathogenic variant status is an ideal example of the future for clinical trials in patients with meningioma (NCT02523014)." (PMID 33262459, 2021). "Two brain invasive meningiomas, both localized at the anterior medial skull base (olfactory groove), had alterations in the PI3K-AKT-mTOR pathway, consisting of AKT1 E17K mutations (1M; 7M), which were mutually exclusive to NF2 alterations." (PMID 33670055, 2021). "Of note, other common pathological relevant genes of meningiomas, including AKT1 (n = 3; 8%), CDKN2A (n = 2; 5%), SMO (n = 0; 0%), SUFU (n = 0; 0%), POLR2A (n = 6; 16%), TRAF7 (n = 1; 3%), and SMARCB1 (n = 2; 5%), were detected as well." (PMID 34778063, 2021). "Meningiomas with Krueppel-like-factor 4 (KLF4)/TNF receptor-associated factor 7 (TRAF7) mutation often locate in the medial skull base and v-akt murine thymoma viral oncogene homolog 1 (AKT1)/TRAF7 mutation in the anterior skull base." (PMID 33042832, 2020). "Each subtype of meningiomas has its own molecular features, but some genetic mutations (including NF2, TRAF7, AKT1, and PIK3CA) can be found among several subtypes of meningiomas, which confuse the judgment of tumor evolution." (PMID 33014773, 2020). "In both studies, AKT1 and PIK3CA mutated meningiomas were primarily located along the midline anterior skull base including olfactory groove, tuberculum sellae, anterior clinoid, and medial sphenoid wing." (PMID 33346248, 2020). "In the present study, all the sample groups had mutations in the meningioma-driver genes such as NF2, AKT1, SMO, TRAF7, and KLF4." (PMID 32742192, 2020). "This new era began with the publication of two landmark genetic sequencing studies in 2013, in which AKT1, SMO, TRAF7 and KLF4 were identified as frequently mutated genes in skull base, WHO grade 1 meningiomas." (PMID 33087175, 2020).